GPX4 (glutathione peroxidase 4)
Diseases named in the same sentence as GPX4 in open-access papers (continued):
Sharing a sentence is not in itself a finding about the gene and the disease.
cancer (continued). "We highlight recent discoveries including BRCA1-dependent ubiquitination of GPX4 and its implications for PARP inhibitor synthetic lethality, NR1D2-mediated transcriptional repression of FSP1, and stromal protection conferred by cancer-associated fibroblasts." (PMID 42231453, 2026). "Research has indicated that genetic inhibition of GPX4 can induce ferroptosis in cancer cells and inhibit cancer growth in vivo." (PMID 41439136, 2026). "ZDHHC20‐mediated palmitoylation of GPX4 at Cys66 site enhances GPX4 protein stability and promotes cancer progression by inhibiting ferroptosis, which can be reversed by APT2." (PMID 41126755, 2026). "LRP8 degradation reduces the abundance of several selenoproteins, including GPX4, lowering the cellular threshold for lipid peroxidation and sensitizing cancer cells to ferroptosis." (PMID 42239248, 2026). "By focusing on the NeuroD1/GPX4 axis, the study clarified the fundamental mechanism of ferroptosis in cancer cells and provided an achievable new strategy for future treatments." (PMID 41439136, 2026). "Glutathione peroxidase 4 (GPX4) is a master regulator of ferroptosis, a process that has been proposed as a potential therapeutic strategy for cancer." (PMID 41259048, 2026). "Generally, this evidence demonstrates the potential impact of LRP8 on the expression of GPX4 in cancer and immune cells." (PMID 41139700, 2026). "Combining HMGCR inhibitors with GPX4 inhibitors exerts anti-cancer effects in therapy-resistant cancer cells with a high-mesenchymal phenotype." (PMID 41596341, 2026). "Special emphasis is placed on the unique role of GPX4 in regulating ferroptosis, a promising target for novel anti-cancer strategies, and on the prognostic significance of TXNRD overexpression in aggressive malignancies." (PMID 41897458, 2026). "LRP8 modulates cancer ferroptosis by regulating selenocysteine levels, which are required for translation of the selenoprotein GPX4." (PMID 41139700, 2026). "GPX4 plays crucial role in promoting cancer cell survival, especially in cancer phenotypes with feature of dedifferentiated states or stem cell-like." (PMID 41341590, 2025). "In vitro studies have shown that targeting GPX4 can induce ferroptosis in chemotherapy-resistant cells, highlighting the therapeutic potential of the ferroptosis pathway in treating drug-resistant cancers." (PMID 39949740, 2025). "GPX4 expression levels were highly reliable in separating cancer from normal tissue, especially in THCA, KIRP, UCEC, READ, LIHC, ESCA, and COAD, where the area under the curve (AUC) exceeded 0.8." (PMID 41142608, 2025). "Many GSH-utilizing enzymes with altered expression patterns in cancers are found in mitochondria, most notably glutathione peroxidase 4 (GPX4) which is a major regulator of the ferroptosis pathway." (PMID 39934670, 2025). "For example, when used in combination with GPX4 inhibitors, cancer cells and xenograft tumors increase sensitivity to the chemotherapy drug gemcitabine by inducing ferroptosis." (PMID 40733146, 2025). "This parallels the emerging therapeutic potential in animals, where GPX4-regulated ferroptosis is being explored as a strategy for treating diseases such as cancer." (PMID 40051871, 2025). "Similar to cancer cells undergoing ferroptosis, GPX4 protein instability in naïve ESCs after bME depletion was restored by treatment with carfilzomib, a proteasome inhibitor." (PMID 40010136, 2025). "Conversely, cancers with high GPX4 expression display relative resistance to DHODH blockade, underscoring the interdependence of these parallel systems." (PMID 41369379, 2025). "Numerous studies have investigated the therapeutic effects of drugs targeting ferroptosis-related molecules such as GPX4 and xCT on various types of cancers." (PMID 40619484, 2025). "In solid tumors, the process by which cancer cells generate selenoproteins, especially GPX4, through selenium metabolism constructs a defense mechanism against ferroptosis." (PMID 41323827, 2025).
cancer (continued). "Our findings are consistent with previous studies showing that GPX4 inhibition is especially effective in eliminating therapy-resistant or metabolically adaptive cancer cells." (PMID 40524253, 2025). "Emerging evidence indicates that targeting GPX4 to enhance ferroptosis has potential as a viable therapeutic approach, especially in the field of cancer treatment." (PMID 40191731, 2025). "Accumulating evidence indicates that GPX4-resistant cancer cells heavily rely on ferroptosis suppressor protein 1 (FSP1), which acts as a critical node integrating multiple protective pathways." (PMID 40862825, 2025). "Although inhibition of either xCT/GSH/GPX4 (by BSO) or xCT-cysteine/CoA/TXNRD2 (by PANKi) alone can be tolerated in cancer cells, their combination leads to synthetic lethality." (PMID 40694424, 2025). "Our findings unequivocally demonstrate that inactivation of mitochondrial respiratory chain complex I (MCI) induces lipid peroxidation and consequently invokes ferroptosis across GPX4 low-expression cancer cells." (PMID 40185704, 2025). "In TNBC MDA-MB-231 cells, radiotherapy upregulates GPX4 expression and suppresses its lysosomal degradation, bolstering cancer cell defenses against ferroptosis and radiotherapy." (PMID 41471274, 2025). "Withaferin A, another plant-derived compound, binds covalently to the active site of GPX4 and promotes ferroptotic death in resistant cancer types." (PMID 40650229, 2025). "Targeting GPX4 is considered a promising therapeutic strategy for inducing ferroptosis to treat cancer, as GPX4 can effectively inhibit lipid oxidation." (PMID 40537877, 2025). "To further characterize the function of LDHB in suppressing lipid peroxidation-associated cell death, we combined LDHB silencing with RSL3 treatment, which irreversibly blocks GPX4, an essential regulator of ferroptotic cancer cell death." (PMID 40090955, 2025). "As a pivotal antioxidant effector, GPX4 is frequently upregulated by cancer cells to counteract oxidative stress and sustain malignant progression." (PMID 40746894, 2025). "Based on these findings, we propose that GPX4 plays a critical role in cancer development and progression." (PMID 41142608, 2025). "For example, RSL3 increases the anti-cancer effectiveness of cisplatin by regulating Gpx4-dependent ferroptosis." (PMID 40843357, 2025). "It promotes ferroptosis by inhibiting the activity of GPX4, thereby enhancing the effect of cancer radiotherapy." (PMID 40009842, 2025). "GPX4 represents a central enzyme in the predominant defense mechanism against ferroptosis in cancer cells." (PMID 40595451, 2025). "In numerous studies targeting ferroptosis and autophagy in cancer cells, GPX4 has emerged as a key factor, with its activity playing a crucial role in solid tumors and related diseases." (PMID 41323827, 2025). "The chromatin remodeling activity of BAP1 directly represses SLC7A11 transcription by removing H2AK119ub1, making BAP1‐mutant cancers hypersensitive to GPX4 inhibitors." (PMID 40919133, 2025). "Initially, we used the Cancer Genome Atlas (TCGA) database to analyze the expression of the ferroptosis-related genes GPX4 and those belonging to the TMEM family in GC samples." (PMID 40223081, 2025). "Nuclear factor kappa B (NF‐κB) activation, NOD‐like receptor family pyrin domain‐containing 3 (NLRP3) inflammasome signaling, and GPX4/GSH depletion emerge as common denominators across cancer progression and inflammatory tissue injury." (PMID 40919133, 2025). "In conclusion, these findings highlight that MWDT exerts its anti-cancer effects by modulating the PTK2B/GPX4 signaling pathway." (PMID 41166024, 2025). "Meantime, Viswanathan's work highlighted that lipid peroxidase pathway inhibition is prevalent in therapy‐resistant cancers, suggesting GPX4 and lipid peroxidation as therapeutic targets to combat drug resistance." (PMID 40900810, 2025).
cancer (continued). "It was previously shown that inhibition of GPX4 can induce the death of cancer cells resistant to conventional chemotherapy." (PMID 40436830, 2025). "N6F11 activates the E3 ubiquitin ligase tripartite motif containing 25 (TRIM25) to mediate GPX4 degradation and has been shown to be selective for cancer cells." (PMID 40998801, 2025). "Previous studies have shown that BECN1 influences ferroptosis through the xCT/GPX4 pathway in various types of cancer cells." (PMID 39940841, 2025). "Within the context of cancer biology, GPX4 serves as a pivotal regulator and central inhibitor of ferroptosis, while FTH1 functions as a crucial iron storage protein." (PMID 40610429, 2025). "Previous studies have revealed the regulatory role of lipids in GPX4-mediated ferroptotic cancer cell death." (PMID 41008983, 2025). "GPX4, a primary enzyme, constitutes the main surveillance system that defends against ferroptosis in cancer cells, primarily through the SLC7A11-GSH-GPX4 signaling axis." (PMID 40595451, 2025). "For instance, targeting key regulators, such as GPX4 or Sx C-, has shown potential in sensitizing cancer cells to conventional therapies." (PMID 39935430, 2025). "In our study, we found that GLS1 knockout increases cancer cell sensitivity to ferroptosis by downregulating GPX4." (PMID 40259435, 2025). "The results unveil a novel PRDX5/GPX4/SIAH2/WSB1 signaling axis as a promising therapeutic vulnerability for cancer." (PMID 40831323, 2025). "The overexpression of GPX4 constitutes the one of major surveillance systems to defend against ferroptosis in cancer cells." (PMID 39297393, 2025). "Many cancers elevate GSH levels and activate GPX4 to counteract oxidative damage caused by therapies." (PMID 39935430, 2025). "In cancer therapy, direct inhibition of GPX4 is proposed as a superior strategy for inducing ferroptosis in cancer cells compared with disrupting GSH27, despite challenges such as poor selectivity and insufficient in vivo antitumor effects." (PMID 40164758, 2025). "Dihydroartemisinin (DHA) enhances GPX4 inhibition-induced ferroptosis by increasing free iron levels, sensitizing ferroptosis-resistant cancer cells." (PMID 39935430, 2025). "The unique vulnerability of drug-tolerant persister cancer cells is highly dependent on mitochondrial respiration and the antioxidant enzyme GPX4 (Glutathione Peroxidase 4) for survival." (PMID 41304766, 2025). "Most importantly, PCBP 1/2 and GPX4 are highly expressed in most human cancers (Human Protein Atlas)." (PMID 40619432, 2025). "Collectively, these pan-cancer analyses underscore the potential of GPX4 as a therapeutic target and biomarker in multiple cancers." (PMID 41142608, 2025). "Beyond enhancing the efficiency and specificity of GPX4 inhibition, another promising direction in cancer therapy involves promoting cell death through combination therapies." (PMID 40164758, 2025). "This section establishes that activation of the cGAS-STING pathway drives ferroptosis in multiple cancers through interconnected mechanisms: inducing autophagy (degrading GPX4), promoting mitochondrial fusion/mitophagy, and triggering ferritinophagy." (PMID 40846966, 2025). "Elevated FSP1 expression confers resistance to GPX4 inhibitor-induced ferroptosis across multiple cancer types, including TNBC, whereas the genetic ablation of FSP1 markedly sensitizes TNBC cells to ferroptosis-inducing agents." (PMID 40862825, 2025). "Paradoxically, upon GPX4 ablation, some cancer cell lineages remain resistant to ferroptosis revealing the existence of compensatory GPX4 independent defense mechanisms." (PMID 41035634, 2025). "The NRF2 pathway transcriptionally regulates the expression of SLC7A11 and GPX4 to inhibit ferroptosis in cancer cells." (PMID 40223081, 2025). "Simvastatin inhibits the expression of 3-hydroxy-3-methylglutaryl coenzyme A reductase (HMGCR), downregulating the mevalonate pathway and GPX4, thereby inducing ferroptosis in cancer cells." (PMID 40136455, 2025).
cancer (continued). "However, the regulatory mechanisms underlying GPX4 regulation in cancer are still unknown." (PMID 40746894, 2025). "In conclusion, GPX4 shows aberrant expression patterns and is correlated with clinical outcomes and immune responses across a broad pan-cancer analysis." (PMID 41142608, 2025). "Increasing lipid peroxidation and total ROS production and decreasing GPX4 activity in tested cancer cell lines were attributed to gallic acid." (PMID 40227202, 2025). "Inactivation of SLC7A11 or GPX4 can restore the radiosensitivity of radioresistant cancer cells and xenograft tumors." (PMID 40102409, 2025). "The discovery of GPX4 inhibitors represents a promising therapeutic approach because of their unique mechanism of action in combating therapy-resistant cancer cells." (PMID 40576928, 2025). "Limiting selenium in cancer cells has been shown to lead to the induction of ferroptosis through ribosome stalling and rapidly reduced expression of GPX4." (PMID 38949989, 2025). "This study pioneers the discovery of a small molecule inhibitor that targets both PCBP1/2 and GPX4, offering a novel therapeutic strategy for eliminating cancer cells through ferroptosis." (PMID 40619432, 2025). "Aberrant overexpression of GPX4 in cancer cells enhances resistance to ferroptosis and supports tumor survival under oxidative stress." (PMID 40947430, 2025). "Using our integrated multi-omics, we discovered a crosstalk network of GPX4 in pan-cancers, providing mechanistic support for developing broad-spectrum therapies - a key advancement beyond the descriptive findings in recent reviews." (PMID 41142608, 2025). "Powerful GPX4 inhibitors such as compound 26a can induce ferroptosis, which has potential application value in cancer treatment." (PMID 40143112, 2025). "These agents illustrate the potential for both the direct and indirect pharmacologic inhibition of GPX4 in cancer therapy." (PMID 40650229, 2025). "In the autophagy mediated by copper and erastin (a ferroptosis inducer), the autophagy receptors TAX1BP1 and SQSTM1 can promote the degradation of GPX4, effectively reducing the resistance of cancer cells to ferroptosis." (PMID 41323827, 2025). "GPX4 inhibition effectively sensitizes resistant cancer cells to ferroptosis, particularly in malignancies such as clear-cell carcinomas, where oxidative stress is a critical vulnerability." (PMID 39935430, 2025). "Evidence demonstrates that abnormal expression of GPX4 is related to cancer initiation and progression." (PMID 40746894, 2025). "Another antioxidant enzyme, HO-1, plays a dual role in cancer, preventing the cancer cells from apoptosis and autophagy, but also inducing ferroptosis, which is generally accompanied by GPX4 inhibition." (PMID 40427716, 2025). "Next, we estimated GPX4 expression in paired cancer tissues and adjacent normal tissues using TCGA datasets." (PMID 41142608, 2025). "GPX4 knockout or its pharmacological inhibition directly induced ferroptosis across various cancer types." (PMID 40276370, 2025). "Studies in human cell lines and xenograft models of colon cancer also revealed that luteolin upregulated a tumor suppressor (hypermethylated in cancer 1) gene expression to induce GPX4 suppression and ferroptosis in cancer cells." (PMID 40227202, 2025). "There is increasing evidence that targeting GPX4-induced ferroptosis is a promising treatment strategy for diseases, especially cancer." (PMID 40136465, 2025). "Using the cBioPortal web server, we investigated genetic alterations of GPX4 across a range of cancers." (PMID 41142608, 2025). "In vivo, KFL2 overexpression significantly inhibits GPX4 transcription, preventing cancer cells from migrating and invading." (PMID 40969276, 2025).
cancer (continued). "Conversely, GPX4 is known to act as an oncogene that inhibits ferroptosis in cancer cells and reduces their drug resistance to established anticancer agents." (PMID 41463386, 2025). "Currently, targeting GPX4 for inducing ferroptosis and promoting cancer cell death has been proven to be a new strategy for cancer treatment." (PMID 40537877, 2025). "The inhibition of the PAR1/JAK2/STAT3 axis downregulates GPX4 in HNSCC cancer cells, enhancing their sensitivity to ferroptosis inducers." (PMID 40650229, 2025). "As a glutathione - independent ferroptosis suppressor, FSP1, by regulating the CoQ10 and NADPH pathways, collaborates with GPX4 to inhibit phospholipid peroxidation and ferroptosis, providing new targets and strategies for cancer treatment." (PMID 40735482, 2025). "Ferroptosis in cancer cells revolves around three cellular pathways: (i) iron metabolism, leading to accumulated iron; (ii) diminished antioxidant defense through the GPX4/GSH pathway; and (iii) metabolism of amino acids." (PMID 40212453, 2025). "Gi-F significantly inhibits GPX4 activity in cancer cells, increasing the possibility of ferroptosis." (PMID 40959280, 2025). "Beyond GPX4, cancer cells utilize mechanisms such as SIRT2-regulated desuccinylation of GCLC to boost glutathione synthesis, conferring ferroptosis resistance under oxidative stress." (PMID 40919170, 2025). "In the realm of solid tumor research, a wealth of findings has elucidated that GPX4 in cancer cells assumes a central role in countering ferroptosis‐induced cell death, thereby serving as a critical determinant for the survival of cancer cells." (PMID 41323827, 2025). "The CancerSEA database was used to investigate the expression pattern of GPX4 at the single-cell level and its functional implications in cancer biology." (PMID 41142608, 2025). "Cancer cells often prevent ferroptosis through upregulation of the selenoprotein glutathione peroxidase 4 (GPX4), which blocks ferroptosis by converting toxic lipid peroxides into nontoxic lipid alcohols." (PMID 38949989, 2025). "Several ferroptosis inducers can directly bind to and reduce GPX4 levels or sensitize cancer cell lines to GPX4 inhibition." (PMID 41326356, 2025). "To further investigate the differences in response to the tipifarnib and RSL3 combination treatment in the different CLs, we used recently published drug sensitivity data where several GPX4 inhibitors were tested in cancer CLs." (PMID 39995872, 2025). "Mechanistic investigations revealed that ZnAMTC functions by reducing intracellular glutathione (GSH) levels and inhibiting glutathione peroxidase 4 (GPX4) activity upon US exposure, thus inducing ferroptosis in cancer cells." (PMID 40034805, 2025). "Hu’s work demonstrated that evodiamine exhibits anti-cancer activity by suppression of GPX4 and induction of ferroptosis." (PMID 40420092, 2025). "GPX4 plays a crucial role in inhibiting ferroptosis, which represents a significant mechanism by which cancer cells resist cell death." (PMID 41323827, 2025). "Epigallocatechin gallate (EGCG) suppresses GPX4 activity and blocks NRF2-dependent antioxidant response, thereby making cancer cells more susceptible to ferroptosis." (PMID 40733290, 2025). "NRF2 serves as a transcription factor that binds to the antioxidant response elements of SLC7A11 and GPX4 to suppress ferroptosis in cancer cells." (PMID 40223081, 2025). "Reducing GPx4 degradation through ubiquitination has become a therapeutic focus for a variety of illnesses, including neurological disorders and cancer." (PMID 41497577, 2025). "IR also induces an adaptive response involving SLC7A11 or GPX4 to inhibit IR-induced iron-dependent cell death and promote the survival of cancer cells during radiotherapy." (PMID 40219018, 2025). "New derivatives of Artesunate can exert cytotoxic effects on various cancer cell lines by inducing GPX4-mediated ferroptosis." (PMID 40758729, 2025).